FGFR3 (fibroblast growth factor receptor 3)
Diseases named in the same sentence as FGFR3 in open-access papers (continued):
Sharing a sentence is not in itself a finding about the gene and the disease.
tumor (continued). "The concentration of FGFR3 in tumor tissue is positively correlated with the primary tumor size and the recurrence probability." (PMID 33935756, 2021). "It has been reported that the levels of FGFR2 and FGFR3 strongly correlate with poor tumour differentiation." (PMID 33179425, 2021). "Among these upregulated PRC2+-CGI genes, we found many well-defined oncogenes and genes encoding tumor-promoting factors such as MYB, TWIST1, SYK, TEAD4, FOXC1, and FGFR3." (PMID 33931649, 2021). "The resulting dimerization of monomers allows us to quantify the temporal changes in fractional occupancy of active FGFR3 dimers in the system and their impact on tumor growth dynamics." (PMID 34984415, 2021). "In this study, we first reported the comprehensive pan-cancer profile of FGFR3 genetic alterations and their prognostic and clinical implications across various cancer types of TCGA which was covering over ten thousand tumor samples." (PMID 34160364, 2021). "The most robust data on anti-tumour activity and efficacy have been generated from trials using pan-FGFR inhibitors—specifically, trials in urothelial cancers with FGFR3 mutations and iCCA with FGFR2 fusions." (PMID 33268819, 2021). "We validated the presence of FGFR3 by IHC staining in the tumor tissue at resection prior to nintedanib application." (PMID 34046693, 2021). "In subset analysis, the positive predictive value of MSA for recurrent disease is much higher in patient groups with an FGFR3 wild-type from resected tumor samples, as it reaches 100% at 24 months of follow-up." (PMID 34884669, 2021). "A total of 42 somatic hot spot mutations were detected in tumor tissue DNA, and 39 mutations were detected in CTC-DNA, all of which included common changes in PTEN, MET, EGFR, RET, and FGFR3." (PMID 34178679, 2021). "Our results show that pretreatment with anti-PD-L1 therapy leads to greater tumor reduction than pretreatment with anti-FGFR3 therapy." (PMID 34984415, 2021). "Multi‐analyte profiling of freshly biopsied tumor sample indicated FGFR3 amplification along with sensitivity of tumor cells towards various chemotherapy drugs." (PMID 34765202, 2021). "FGF9 binds to FGFR3 IIIb or IIIc and enhances cell line migration by inducing gaps in monolayers of blood or lymphatic endothelium, similar to tumor invasion into the circulation." (PMID 33802841, 2021). "Tumor volumes of a FGFR3 K650N xenograft were significantly decreased in both drug groups compared with the vehicle group." (PMID 34272467, 2021). "Additional downstream pathways in this tumor-suppressive context include Cbl-dependent ubiquitin downregulation of Lyn and Fyn kinases and/or bystander effects on FGFR3-expressing stromal cells." (PMID 34007277, 2021). "Our mutational analysis shows FGFR3 mutation both on epididymal BT and liver metastasis, while PIK3CA mutation was only present in the primary tumor." (PMID 33912469, 2021). "Our model formulation allows us to track the fraction of active FGFR3 dimers and to use this quantity to augment the rates of tumor cell division and tumor cell death, which is mediated by cytotoxic T cells." (PMID 34984415, 2021). "As the fibrin cluster, the peptidase cluster contained many differentially overexpressed MMPs, including MMP2, in the LMS4/F2T2↑ tumor but also in FGFR3 tumors." (PMID 33853673, 2021). "We also provide a roadmap for the rational clinical development of targeted and immunotherapeutic strategies that are specific to UTUC, but also potentially applicable to other tumor types harboring FGFR3-activating molecular alterations." (PMID 33397444, 2021).
tumor (continued). "In cell line models expressing mutants FGFR2 W290C and S320C, or FGFR3 R248C and S249C, infigratinib was able to reduce the transformation properties of these cells in anchorage-independent conditions and reduce tumour volume in xenograft mouse models." (PMID 34068816, 2021). "It has been shown that there was FGFR3 up regulation in a sample of BCa tumor tissues compared with normal mucosa." (PMID 32795296, 2020). "For example, over 30% patients had positive FGFR1 expression in UCEC, OV, KICH, and ACC, whereas the positive ratios of FGFR3 were very low in these tumor types." (PMID 32596330, 2020). "Tumors with an FGFR3 fusion tended to be of PUNLMP in tumor grade (p = 0.056): five out of the seven cases (71.4%) with FGFR3 fusion were of PUNLMP." (PMID 32012866, 2020). "Upregulation of mTOR and fibroblast growth factor receptor 3 (FGFR3) inhibits tumour growth activated by tyrosine-protein kinase cellular sarcoma (c-SRC)." (PMID 33023154, 2020). "The activation of the FGFR3 signaling pathway can promote tumor growth, metastasis, and drug resistance." (PMID 33381388, 2020). "For example, XL999, which targeting FGFR3, has the potential to prevent tumor growth and has been investigated for the treatment of unspecified cancer/tumors." (PMID 32528533, 2020). "Genetic alterations in FGFR1, FGFR2,and FGFR3 are reported in many tumor types and include all of the mechanismsdescribed leading to constitutive activation of the receptors or aberrantligand-dependent signaling through FGFRs." (PMID 32315352, 2020). "Mutations of HRAS, FGFR3, PIK3CA and TERT were found in 2.9%, 27.2%, 14.9% and 76.7% of tumor samples, respectively." (PMID 33024200, 2020). "This is too small a number for meaningful comparisons with our results, except for one tumor with the FGFR3 fusion mentioned in the results." (PMID 32012866, 2020). "The tumors were subtyped by gene expression profiling and analyzed for hotspot mutations in FGFR3, PIK3CA and TERT, the most frequent early driver mutations in this tumor type." (PMID 31609466, 2020). "These and other microRNAs influence tumor progression via the regulation of gene activities, including expression of fibroblast growth factor receptor 3 gene (FGFR3)." (PMID 33238591, 2020). "Based on the recent studies, we narrowed our current research focus on three molecular pathways—immune checkpoint axis PD1/PD-L1, fibroblast growth factor receptor 3 expression status, and tumor-dependent miRs." (PMID 33238591, 2020). "Exon sequencing of 409 cancer-related genes identified enrichment of somatic mutations in FGFR3 and FGFR4 in the recurrent tumor compared with the treatment-naïve tumor, indicating a pivotal role for FGFR signaling in cancer cell survival through CIRT." (PMID 31540114, 2019). "Blocks with the sections containing the tumor and adjacent normal epithelium were chosen for the immunohistochemical (IHC) study of FGFR3." (PMID 31528172, 2019).
tumor (continued). "R3P can efficiently deliver siRNA into FGFR3-positive tumor cells, and induce cell apoptosis by decreasing the expression of oncogenes." (PMID 31535232, 2019). "This strategy is also potentially applicable to other tumor types harboring FGFR3-activating molecular alterations." (PMID 31278255, 2019). "A recent study investigating gene expression using single-cell RNA-Seq in GBM patients found that FGFR3 expression is five-fold higher in invasive GBM cells compared to the tumor core." (PMID 31337028, 2019). "Fibroblast growth factor receptor 3 (FGFR3) plays an important regulatory role in tumor cell proliferation and drug resistance." (PMID 31535232, 2019). "ScFv-9R can both bind siRNA and deliver siRNA into FGFR3 positive cancer cells via silencing specific gene expression to suppress tumor growth." (PMID 31535232, 2019). "Based on this knowledge, we provide a roadmap for the rational clinical development of targeted and immunotherapeutic strategies that are specific to UTUC but also potentially applicable to other tumor types harboring FGFR3-activating molecular alterations." (PMID 31278255, 2019). "Somatic mutations in the genes encoding VEGFR2, FGFR1, FGFR2, FGFR3, and KRAS were identified in the patient's tumor tissue." (PMID 30792968, 2019). "They exhibited potent antitumor activity against a panel of tumor cell lines, including HCT-116 and HepG2, with IC50 values < 10 μg/mL, in addition to inhibitory activity against tumor growth-related tyrosine kinases, including FGFR3, IGF1R, PDGFRb, and TRKB." (PMID 31174259, 2019). "This was supported molecularly by stratified expression of basal urothelial markers; for example, KRT5 expression and proliferation limited to the basal and suprabasal layers, and high tumor‐cell expression of FGFR3 in all cell layers." (PMID 29791078, 2018). "In general, these strategies were found to be effective at inhibiting FGFR3 activity, reducing cell proliferation, and in some cases significantly reducing tumor growth in mouse xenoplant assays." (PMID 29423038, 2018). "High expression levels of FGFR3 contribute of tumour initiation and early-stage progression in HNSCC." (PMID 29377909, 2018). "FGFR3 is considered a potential therapeutic target in UC, because recent studies show that FGFR3 activation is an important contributor to tumor development and angiogenesis in UC." (PMID 30064409, 2018). "BGJ398 is an orally available selective inhibitor of FGFR1, FGFR2, and FGFR3 that has been shown to potently inhibit tumor cell proliferation and tumor growth in various cancer models harboring genetic alterations in FGFR1/2/3." (PMID 30326563, 2018). "Biologically activated FGFR3 signaling promotes cell proliferation and tumor growth, however interestingly, highest numbers of FGFR3-alterations are found in benign papillary or low grade papillary tumors with usually low proliferation (Ki67) index." (PMID 30154342, 2018). "Both in NMIBC and in MIBC there was a significant coincidence of CDKN2A deletions and activating mutations of FGFR3 and NMIBC tumours with this feature had an increased progression rate." (PMID 30258198, 2018). "Of the 11 SpTs in which FGFR3/HRAS/NRAS mutations have been identified so far, chromosomal copy number information is available for only one tumor (SS2) from an 84 year old man." (PMID 28542371, 2017).
tumor (continued). "We conclude that the overexpression of FGF-2 and the overexpression or genetic alteration of FGFR-3 occur in minimally overlapping tumor sets." (PMID 28515962, 2017). "In a comprehensive survey of gene fusions across different solid tumor histologies, the authors described a wide-ranging distribution of FGFR1, FGFR2, and FGFR3 fusions across 8 of 20 tumor types analyzed." (PMID 28030802, 2017). "Consistently, neutralization of IGF-1 in TAB-tumor cell co-cultures led to inhibition of FGFR-3 induction and FGF-2 secretion by tumor cells." (PMID 28928360, 2017). "Other upstream genes of ERK signaling pathway such as EGFR, FGFR3 were also enriched in resistant tumor cells." (PMID 29296238, 2017). "FGF-2/FGFR-3 signaling is involved in angiogenesis, tumor progression, and therapy resistance in other cancers." (PMID 28928360, 2017). "Tumours in this subset expressed FGFR3 and CCND1 as determined by IHC at the same levels as the Uro tumours, indicating a Uro‐related phenotype." (PMID 28195647, 2017). "For example, low levels of miR-100 were correlated with low-grade, non-invasive bladder urothelial cancer, due to the upregulation of FGFR3, meaning that, under physiological conditions, miR-100 acts as a tumor suppressor." (PMID 29165379, 2017). "We performed whole-exome (paired tumor and germline DNA) and transcriptome (tumor RNA) sequencing, which demonstrated an FGFR3-PHGDH fusion." (PMID 29872711, 2017). "Consistent with FGFR3 expression, FGFR1 immunostaining was significantly associated with a higher tumor grade (p < 0.05, Fisher’s exact test) and cerebral location (p < 0.01, Fisher’s exact test)." (PMID 28468611, 2017). "The main functions of the top genes in OSPC2 network were associated to sensitization to chemotherapy (CXCR4, ANKRD1, CYR61, EDN1, ATP1B1, ARHGEF1, RTF1), and tumor suppression (FGFR3, BCL11B)." (PMID 28482906, 2017). "The calculated genomic circuit scores were, as expected, high for tumours in the Uro cluster, i.e. FGFR3+, CCND1+, RB1+, and E2F3−, both at the mRNA level and the tumour‐cell protein level." (PMID 28195647, 2017). "NIH/3T3 cells over expressing mutant and wild-type FGFR3 constructs were characterized for anchorage independent growth, constitutive activation, tumor formation and sensitivity to FGFR inhibitors using in vitro and xenograft mouse models." (PMID 27998968, 2017). "Recombinant IGF-1 increased tumor cell expression of FGFR-3 as did co-cultured TAB cells, and reciprocally, recombinant FGF-2 induced IGF-1 production in NB cells as did co-cultured tumor cells." (PMID 28928360, 2017). "After shRNA interference with FGFR-3 expression, tumor cells lost their resistance against BRAFi and MEKi in co-cultures with TAB cells." (PMID 28928360, 2017). "The relative figures for FGFR3 mutation alone in stage/grade tumors were in 46.0 % pTa, 28.0 % pT1, 16.7 % CIS, 30.0 % other tumor stages, 53.0 %/23.9 % low/high-grade." (PMID 27586786, 2016). "We recently demonstrated for FGFR3 IIIc oncogenic functions by a gain of broader ligand specificity important for CRC tumor progression." (PMID 27650542, 2016).
tumor (continued). "Due to its contribution to tumor development, FGFR3 is an interesting therapeutic target and targeted therapies aimed at FGFR3 are emerging." (PMID 26711175, 2016). "Using the combination of FGFR3 mutation and methylation, the detection of recurrence was significantly increased with 96.4 % pTa, 100 % pT1, 100 % CIS, 50.0 % other tumor stages, 93.6 %/96.0 % low-/high-grade tumors." (PMID 27586786, 2016). "As it has been demonstrated by Zuiverloon, sensitivity for FGFR3 assay is correlated with the number of shed low-grade tumor cells." (PMID 27586786, 2016). "Though, the contribution of FGFR3 protein overexpression to tumor progression seems to be tumor‐type dependent." (PMID 26711175, 2016). "In our study of primary tumours, the percentage of TERT and FGFR3 reads containing mutations varied continuously from undetectable to >50% of the total reads." (PMID 26901314, 2016). "On the other hand, FGFR3 negatively related genes demonstrated tumor related functions, such as mitosis and cell cycle, which indicated frequent cell proliferation." (PMID 27829236, 2016). "All tested FGFR3-TACC3 positive tumors showed strong expression of FGFR3 by tumor cells on immunohistochemistry (IHC)." (PMID 27409839, 2016). "Occurrence of more than one mutation for FGFR3 and TERT has been found before and is probably due to either tumor heterogeneity or the presence of multiple tumor clones in the bladder." (PMID 27611947, 2016). "This is the first study reporting that the loss of Fgfr3 function leads to the formation of chondroma-like lesions via downregulation of MEK/ERK signaling and upregulation of IHH, suggesting that FGFR3 has a tumor suppressor-like function in chondrogenesis." (PMID 26091072, 2015). "Based on these findings, we propose that FGFR3 has a tumor suppressor-like function in cartilage development." (PMID 26091072, 2015). "Based on these results, we propose a model for cartilaginous tumor development in which FGFR3 functions as a tumor suppressor." (PMID 26091072, 2015). "In vivo treatment of PDX model LTL392 with an inhibiting antibody targeting FGFR3 (R3Mab) strongly inhibited tumor growth." (PMID 26041878, 2015). "Both FGFR3 and eIF4E have been shown to promote tumor growth, and are overexpressed in human cancers including CRC." (PMID 26078354, 2015). "Cytoplasmic FGFR-3 expression was observed in upper and middle layers of lining epithelium, stromal fibroblast cells, tumor cells and sometimes in the endothelium of tumor stroma." (PMID 26465941, 2015). "Although many genes were downregulated in GB-1 3D culture relative to the parental tumor (e.g. FGFR3, TGFβ1 and TYMP), certain genes were now upregulated (e.g. FGF2, ANGPT1 and EFNA3)." (PMID 26203665, 2015). "Exploratory biomarker analysis showed FGFR3, FGFR1, FGF-ligand and fibroblast growth factor receptor substrate 2 (FRS2) expression in the patient’s tumour, together with the presence of a germ-line mutation in the FGFR3 extracellular binding domain." (PMID 26497743, 2015). "Ten variants were identified from eight genes in both the tumor and normal groups (APC, EGFR, FGFR3, KDR, MET, PDGFRA, RET and SMO)." (PMID 25404506, 2014). "The present data raise the possibility that FGFR3 has biphasic effects during multistage carcinogenesis in carcinomas, acting first as a tumor suppressor through oncogene-induced senescence via STATs activation and apoptosis enhancement." (PMID 23902722, 2013).